RNU2-69P (RNA, U2 small nuclear 69, pseudogene)
Gene: Small nuclear RNA gene on chromosome 18 (58,926,197 to 58,926,296, reverse strand). Ensembl gene ENSG00000251870.
Homologues: Orthologues: macaque U2 (64% identical), rabbit U2 (60% identical), tropical clawed frog U2 (58% identical), guinea pig U2 (55% identical). Paralogues in human: RNU2-24P (65% identical), U2 (62% identical), RNU2-41P (61% identical), RNU2-53P (61% identical), RNU2-2 (60% identical), RNU2-42P (60% identical), RNU2-60P (60% identical), U2 (60% identical), RNU2-4P (59% identical), RNU2-6P (59% identical), RNU2-59P (58% identical), RNU2-16P (57% identical), and 64 more.